RAC1 (Rac family small GTPase 1)
Diseases named in the same sentence as RAC1 in open-access papers (continued):
Sharing a sentence is not in itself a finding about the gene and the disease.
gastric cancer (continued). "All of these results suggest that Trio is critical for Rac1 activation and invasive ability of gastric cancer cells." (PMID 35008419, 2022). "All of our results clearly suggest that RhoGDI2 plays an important role in the interaction between Rac1 and Filamin A and Rac1 activation in gastric cancer cells." (PMID 35008419, 2022). "The expression of Rac1 in gastric cancer tissues was detected, and it was found that the expression of Rac1 in TNM III and IV stages was higher than that in I and II stages and was associated with tumor lymph node metastasis." (PMID 34079763, 2021). "It has been reported that GSK3β activates Rac family small GTPase-1 (Rac1), and activation of this gene is involved in breast, colon, bladder, and gastric cancer, indicating a role of Rac1 in tumor development." (PMID 32074995, 2020). "In all, it is concluded that MICAL1 is regulated by NEDD9 that facilitates hypoxia-induced gastric cancer cell migration via Rac1-dependent manner." (PMID 31019460, 2019). "Taken together, GINS4 plays key roles in cell proliferation, cell cycle, apoptosis, migration and invasion of gastric cancer through activating Rac1 and CDC42 and their downstream signaling pathways: MAPK/ERK pathway, PI3K/AKT pathway and PTEN pathway." (PMID 31754397, 2019). "Collectively, a novel circMLLT10/miR-509-3-5p/GINS4/Rac1/CDC42 axis was established in gastric cancer growth and progression." (PMID 31754397, 2019). "IPA revealed that GINS4 plays key roles in cell proliferation, cell cycle, apoptosis, migration and invasion of gastric cancer by Rac1 and CDC42 and their downstream signaling pathways: MAPK/ERK pathway, PI3K/AKT pathway and PTEN pathway." (PMID 31754397, 2019). "Together, these data strongly suggested that ERBB2 was inseparable to induce Rac1 activation and participated in the migration and invasion of gastric cancer cells." (PMID 28099468, 2017). "The migration and invasion of gastric cancer cells was inhibited by miR-1296-5p overexpression or herceptin treatment, and rescued by the overexpression of constitutively active Rac1-Q61L or ERBB2." (PMID 28099468, 2017). "We further advocate that miR-1296-5p can inhibit cell migration by repressing ERBB2 expression and Rac1 activation in gastric cancer cells." (PMID 28099468, 2017). "Taken together, these experiments demonstrated that miR-1296-5p suppressed the Rac1 activation, the migration and invasion of gastric cancer cells." (PMID 28099468, 2017). "Overexpression and overactivation of Rac1 resulted in increased cell proliferative and metastatic capacities in gastric cancer cells." (PMID 27791203, 2016). "In summary, we confirmed that DADS reduces the expression of Rac1, Pak1 and Rock1 in gastric cancer MGC803 cells." (PMID 26871290, 2016). "Expectedly, NKX6.3 significantly decreased the protein expression of RhoA, Cdc42, p-Rac1/Cdc42, and Rac1/2/3 in gastric cancer cells." (PMID 27333045, 2016). "Ji found that Rac1 was related to invasiveness and is a promising therapeutic target for treatment of gastric cancer." (PMID 27791203, 2016). "The correlation among the expression of Rac1, Pak1 and Rock1 in gastric cancer was analyzed using Spearman's rank correlation." (PMID 23298303, 2014). "The possible mechanism of interaction between Rac1, Pak1 and Rock and other genes in gastric cancer deserves further study." (PMID 23298303, 2014). "In the present study, immunohistochemistry and a tissue microarray were used in the detection of Rac1, Pak1 and Rock1 protein expression levels in gastric cancer cells, intraepithelial neoplasia and normal tissues." (PMID 23298303, 2014). "The correlation of Rac1, Pak1 and Rock1 expression in gastric cancer was analyzed using Spearman's rank correlation, and the expression of the three groups in gastric cancer was positively correlated (r = 0.555, P < 0.05)." (PMID 23298303, 2014).
gastric cancer (continued). "RhoGDI2 activates NF-κB in a Rac1-dependent manner; activated NF-κB is critical for Snail upregulation in RhoGDI2-overexpressing gastric cancer cells, indicating the central role of RhoGDI2 in regulating Snail expression and consequently EMT." (PMID 24721928, 2014). "Overall, the present study shows that RhoGDI2 overexpression is involved in acquisition of the mesenchymal phenotype of gastric cancer cells, and that Rac1-dependent NF-κB activation and subsequent Snail expression is essential for induction of EMT." (PMID 24721928, 2014). "Rac1, Pak1 and Rock1 are indicators related to gastric cancer invasion and metastasis, but few reports discuss all three kinds of protein in research on gastric cancer invasion and metastasis." (PMID 23298303, 2014). "RhoGDI2 is a critical regulator of Rac1 in many cancer cells and PLCγ is activated by RhoGDI2 expression in gastric cancer cells." (PMID 24721928, 2014). "Taken together, these results suggest that RhoGDI2-mediated Rac1 activation is important for NF-κB activation, which induces Snail upregulation in gastric cancer cells." (PMID 24721928, 2014). "The aim of this study was to investigate the expression and clinical significance of Rac1, Pak1 and Rock1 in gastric carcinoma." (PMID 23298303, 2014). "The Rac1 expression rates in the normal gastric tissue, intraepithelial neoplastic tissue and gastric carcinoma were 27, 43 and 68 percent, respectively." (PMID 23298303, 2014). "Positive rates of Rac1, Pak1 and Rock1 expression in normal tissue, dysplasia and gastric carcinoma show an increasing trend and are correlated with tumor lymph node metastasis and TNM stage." (PMID 23298303, 2014). "Rac1, Pak1 and Rock1 expression in 158 cases of gastric carcinoma were investigated via immunohistochemical staining and clinical analysis." (PMID 23298303, 2014). "The results indicate that Rac1 expression in normal gastric tissue, intraepithelial neoplastic tissues and gastric carcinoma were 27, 43 and 68 percent, respectively." (PMID 23298303, 2014). "The positive expression rates of Rac1, Pak1 and Rock1 in normal tissue, intraepithelial neoplastic tissues and gastric carcinoma showed an increasing trend (P < 0.05)." (PMID 23298303, 2014). "In 7 gastric cancer cell lines, the expressions of Rac1 were higher than in gastric mucosal epithelial cell line (GES-1), which was coincided with the phenomenon we found with miR-338-3p in gastric cancer cells and tissues." (PMID 23826132, 2013). "In conclusion, the expression of ST3GAL4 leads to SLex antigen expression in gastric cancer cells which in turn induces an increased invasive phenotype through the activation of c-Met, in association with Src, FAK and Cdc42, Rac1 and RhoA GTPases activation." (PMID 23799130, 2013). "This review summarizes the structure, regulatory dynamics, and signaling mechanisms of Rac1 in gastric cancer growth, epithelial-to-mesenchymal transition (EMT), and metastasis, as well as the roles of factors such as hypoxia, oxidative stress, and H. pylori infection." (PMID 41188920, 2025). "Asporin (ASPN), a small proteoglycan, mitigates oxidative stress in gastric cancer cells and activates the Rac1 signaling pathway through the upregulation of cluster of differentiation 44 (CD44), thereby enhancing the migratory and invasive capabilities of these cells." (PMID 41188920, 2025). "However, several natural biological extracts have demonstrated Rac1-inhibitory activity in gastric cancer models." (PMID 41188920, 2025). "However, the prognostic implications of ITGB6 and Rac1 overexpression in gastric cancer patients, as well as their potential interrelationship, remain indeterminate." (PMID 38344200, 2024). "It was found that downregulation of ITGB6 expression and Rac1 activity inhibition could significantly inhibit the migration and invasion ability of gastric cancer cells." (PMID 38344200, 2024).
gastric cancer (continued). "And this point has also been corroborated through immunohistochemistry, revealing that Rac1 is highly expressed in gastric tumor tissue and lymph node metastasis, serving as an independent prognostic factor for gastric cancer patients and leading to poorer overall survival." (PMID 38344200, 2024). "In addition, in vitro experiments including CCK8 and Transwell assays were conducted to explore the roles of ITGB6 and Rac1 in gastric cancer." (PMID 38344200, 2024). "ITGB6 and Rac1 are indicators of poor prognosis and tumor progression in gastric cancer patients." (PMID 38344200, 2024). "Silencing Rac1 and Prex1 could inhibit epithelial–mesenchymal transition, reduce cell viability and migration, and promote apoptosis in human gastric cancer cells." (PMID 37434402, 2023). "At present, the roles and mechanisms of Rac1 and Prex1 in gastric cancer cell EMT are still unknown." (PMID 37434402, 2023). "Similarly, the suppression of RAC1, a member of the Rho family GTPases, inhibits the RAC1-activated ROS generation pathway that promotes metastatic colonization in gastric cancer." (PMID 37237992, 2023). "In this study, we found that RhoGDI2 could enhance the interaction between Rac1 and Trio in gastric cancer cells, which is critical for Rac1 activation and invasive ability in gastric cancer cells." (PMID 35008419, 2022). "Moreover, we found that Filamin A is required for Rac1 activation and the invasive ability of gastric cancer cells." (PMID 35008419, 2022). "Furthermore, we found that Trio, a Rac1-specific GEF, is critical for Rac1 activation in gastric cancer cells." (PMID 35008419, 2022). "We next investigated whether RhoGDI2 could enhance the interaction between Rac1 and Trio in gastric cancer cells." (PMID 35008419, 2022). "Therefore, we reasoned that 14-5-18 treatment would lead to a reduction of the level of active Rac1 and Cdc42 in gastric cancer cells." (PMID 36418900, 2022). "Keeping in mind that enhancing Rac1 activity by RhoGDI2 may be important for the metastasis of gastric cancer, we have identified its mechanism." (PMID 35008419, 2022). "Furthermore, we found that Trio, a Rac1-specific guanine nucleotide exchange factor (GEF), is critical for Rac1 activation and the invasive ability of gastric cancer cells." (PMID 35008419, 2022). "Furthermore, we found that RhoGDI2 regulates Rac1 activity and that Rac1 activation is required for RhoGDI2-induced gastric cancer cell invasion." (PMID 35008419, 2022). "It was reported that knockdown of Piezo1 in gastric cancer cells led to Rac1 activation." (PMID 35428847, 2022). "Therefore, we conclude that RhoGDI2 increases Rac1 activity by recruiting Rac1 to Filamin A and enhancing the interaction between Rac1 and Trio, which is critical for the invasive ability of gastric cancer cells." (PMID 35008419, 2022). "MiR-148b-3p represses gastric cancer cell metastasis by targeting the Dock6/Rac1/cdc42 axis." (PMID 35549631, 2022). "To determine whether Trio is critical for Rac1 activation in gastric cancer cells, we depleted Trio expression in SNU484/GDI2 and MKN28 cells, which led to marked reduction of Rac1 activity in these cells." (PMID 35008419, 2022). "Biochemical molecular analysis revealed that TIPE2 could reduce the activation of RAC1 and MMP9 by binding to RAC1, thereby suppressing gastric cancer cell metastasis." (PMID 34630074, 2021). "Knockdown of RhoGDI2 reduced the mRNA expression of Rac1 in gastric cancer." (PMID 34307388, 2021). "Inversely, Xueping Wang’s group observed that neogenin is over-expressed in gastric cancer, and neogenin could promote gastric cell adhesion by activating the Rac1/PI3K/AKT pathway." (PMID 32318624, 2020). "To test whether Rac1 affected the sensitivity of other cancer cells to chemotherapeutics, we manipulated Rac1 expression in the lung, ovary, and gastric cancer cell lines." (PMID 32193458, 2020).
gastric cancer (continued). "However, our data are in contrast with a report on gastric cancer cells in which the authors suggest that reduced Rac1 activity explains why a WNT5A antibody impairs the migration and invasion of these cells." (PMID 30582770, 2019). "Collectively, these results revealed that NEDD9/MICAL1 may act on Rac1 to affect hypoxia-induced gastric cancer cell migration." (PMID 31019460, 2019). "However, only the upregulation of Rac1-GTP level was observed in gastric cancer cells that were already overexpressed by MICAL1." (PMID 31019460, 2019). "Rac1 activation was increased in NEDD9-overexpressed gastric cancer cells." (PMID 31019460, 2019). "Moreover, we examined the role of ERBB2 and Rac1 signaling on the migration and invasion of gastric cancer cells." (PMID 28099468, 2017). "Taken together, our findings first suggest that miR-1296-5p might be involved in the regulation on the migration and invasion of human gastric cancer cells at least in part via targeting ERBB2/Rac1 signaling pathway." (PMID 28099468, 2017). "Next, we determined the expression of NKX6.3, E-cadherin, N-cadherin, β-catenin, p-GSK3βY216, CLND1, RhoA, Cdc42, Rac1/2/3, Snail, Slug and Vimentin proteins in 7 gastric cancer tissues at different TNM stages and compared with expression in non-tumorous gastric mucosal tissues." (PMID 27333045, 2016). "In addition, we have found that the increased expression of Rac1, Pak1 and Rock1 in primary gastric cancer is correlated with lymph node metastasis, clinical stage and poor prognosis." (PMID 26871290, 2016). "We therefore examined whether suppression of Rac1 or PLC activity affects Snail expression in RhoGDI2-overexpressing gastric cancer cells." (PMID 24721928, 2014). "Rac1, Pak1 and Rock1 expression in gastric cancer was positively correlated (r = 0.555, P < 0.05)." (PMID 23298303, 2014). "The expression of Rac1, Pak1 and Rock1 in normal epithelium and intraepithelial neoplastic epithelium was weakly positive or positive; however, a large number of positively stained cells were heterogeneously distributed in the gastric carcinoma tissues." (PMID 23298303, 2014). "HGF regulates Rac-1-induced ROS production through the Akt pathway and ROS regulates uPA production and invasion via MAP kinase, which provides novel insight into the mechanisms underlying the progression of gastric cancer." (PMID 19497102, 2009). "Additionally, subsequent in vitro experiments preliminarily demonstrated that ITGB6 and Rac1 promoted the proliferation, migration and invasion of gastric cancer cells, and ITGB6 may functions via targeting Rac1." (PMID 38344200, 2024). "In addition, Rac1 promotes the EMT process of cancer stem-like cell phenotypes in gastric cancer, and thus, inhibition of Rac1 may prevent metastasis and augment chemotherapy for cancer." (PMID 36675278, 2023). "Moreover, we tried to determine whether the mutants of GIT1 (GIT1Mut1: GIT1L271A; GIT1Mut2: GIT1L279A) influenced the drug-induced inhibition of gastric cancer cell invasion and Rac1 activation." (PMID 36418900, 2022). "Additionally, Rac1 activity was reduced in FLNA-depleted gastric cancer cells." (PMID 35008419, 2022). "However, the precise molecular mechanism by which RhoGDI2 activates Rac1 in gastric cancer cells remains unclear." (PMID 35008419, 2022). "In this study, to identify the precise molecular mechanism by which RhoGDI2 activates Rac1 activity, we performed two-hybrid screenings using yeast and found that RhoGDI2 plays an important role in the interaction between Rac1, Filamin A and Rac1 activation in gastric cancer cells." (PMID 35008419, 2022). "Therefore, we theorized that FLNA could be a scaffold protein that mediates Rac1 activation via RhoGDI2 in gastric cancer cells." (PMID 35008419, 2022). "It is presumable that RhoGDI2 may act as a Rac1 positive regulator in gastric cancer cells." (PMID 35008419, 2022). "Interestingly, only Rac1 activity was increased in MICAL1-overexpressed gastric cancer cells." (PMID 31019460, 2019).
gastric cancer (continued). "Therefore, it is understood that MICAL1 might stimulate Rac1 activation via PI3K/Akt signaling in gastric cancer cells." (PMID 31019460, 2019). "To determine whether NKX6.3 reduces gastric cancer cell migration through down-regulation of the Rho-GTPase family, we examined the expression of CD2-associated protein (CD2AP), RhoA, Cdc42, p-Rac1/Cdc42 and Rac1/2/3 proteins, in AGSNKX6.3 and MKN1NKX6.3 cells." (PMID 27333045, 2016). "Rac1, Pak1 and Rock1 expression in gastric cancer is closely related with the degree of gastric cancer lymph node metastasis and TNM stage and they play an important role in the invasion and metastasis of gastric cancer and might be key biological markers for invasion and metastasis." (PMID 23298303, 2014). "Rac1, Pak1 and Rock1 may be important biomarkers of gastric carcinoma invasion and metastasis." (PMID 23298303, 2014). "MiR-345 directly targets epidermal growth factor receptor pathway substrate 8 (EPS8), which leads to the inactivation of Rac1 and inhibits cell migration, EMT, and the cancer stem cell phenotype, thereby suppressing gastric cancer metastasis." (PMID 41188920, 2025). "Research indicates that the atypical Rho GEF DOCK6 facilitates the proliferation, migration, and invasion of gastric cancer cells while also enhancing chemo- and radio-resistance via the DOCK6/Rac1/Cdc42 axis and the DOCK6/WNT/β-catenin signaling pathway." (PMID 41188920, 2025). "PlexinA1 interacts with the actin cytoskeleton regulator MICAL1 in a manner dependent on Rac1 and ROS, modulates vimentin expression, and prevents MICAL1 degradation, thereby facilitating gastric cancer cell migration." (PMID 41188920, 2025). "One of the limitations of this study is that it mainly explored the effect of silencing Rac1 and Prex1 on EMT in human gastric cancer in vitro." (PMID 37434402, 2023). "There were different pathways, for example, in gastric cancer, via directly combination with Rac1/CDC42, GINS4 activated Rac1/CDC42 and then influence the downstream pathways." (PMID 35896011, 2022). "We have identified the precise molecular mechanism by which RhoGDI2 recruits Rac1 to FLNA and increases Rac1 activity, which is critical for gastric cancer metastasis." (PMID 35008419, 2022). "Particularly, our previous study indicated that circMLLT10 served as a sponge of miR-509-3-5p, and promoted gastric cancer cell progression through increasing the expression of GINS4 and then activating Rac1 and CDC42." (PMID 34656159, 2021). "In gastric adenocarcinoma, RAC1 overexpression promoted the CSC phenotype, chemotherapy resistance, and expression of SOX2 in spheroids of gastric cancer cells." (PMID 34771704, 2021). "Rac1 overexpression in SKOV-3 (ovary cancer) and ASG (gastric cancer) increased its IC50 dose to DDP treatment, whereas NSC23766 decreased the IC50 doses in these cells." (PMID 32193458, 2020). "We also discussed the down-regulation of N-WASP, PAK and LIMK, downstream of Cdc42 and Rac1, which altered actin organization and was involved in targeting ITGA2 inhibited cell migration of gastric cancer cells." (PMID 29743821, 2018). "Our previous work showed that some Rho GTPases, including Rho, Rac1 and Cdc42, play critical roles in gastric cancer (GC); however, how they are regulated in GC remains largely unknown." (PMID 29587866, 2018). "In this article, our experiment verifies the inhibitive role of miR-1296-5p in the migration and invasion of ERBB2-postive gastric cancer cells that is achieved by suppressing ERBB2 expression and Rac1 activation." (PMID 28099468, 2017). "Overexpressed miR-1296-5p reduced its target protein level and Rac1 activation, and inhibited the migration and invasion of SNU-216 and NUGC-4 gastric cancer cells." (PMID 28099468, 2017). "Recent studies have shown that inhibiting Rac1 activity or knocking down LIMK1 expression abrogated their effects on malignant phenotypes, including increased growth and invasion in gastric cancer cells." (PMID 26871290, 2016).